TLR3 (toll like receptor 3)
Diseases named in the same sentence as TLR3 in open-access papers (continued):
Sharing a sentence is not in itself a finding about the gene and the disease.
prostate carcinoma (continued). "In addition to the proinflammatory effects of TLR-3 stimulation, TLR-3 stimulation in a human prostate cancer cell line (DU145) by IAV expressing IL-24, which is typically responsible for activation of STAT1 and STAT3, was shown to induce apoptotic cell death." (PMID 37974615, 2023). "Although TLR3 can be activated in prostate cancer cells, the molecular signaling pathway has not been fully elucidated." (PMID 25101092, 2014). "Downregulation of TLR3, which detects dsRNA of viral origin and aberrantly methylated endogenous RNAs is apparent from a previous prostate cancer microarray study, but not was not followed up there." (PMID 17280610, 2007). "TLR3 expression was decreased in many, but not all prostate cancers compared to normal tissues." (PMID 17280610, 2007). "The analysis of individual genes by quantitative real-time PCR revealed that many (e.g. MX1, EPB41L3), but not all (notably BCCIP and TLR3) of the genes significant in the interaction analysis were also overexpressed generally in prostate cancers compared to benign tissues." (PMID 17280610, 2007).
encephalitis (32 papers, 2009 to 2025). An acute inflammatory process affecting the brain parenchyma. "(2002) evaluated the TLR3 rs3775291 C/T polymorphism in tick-borne viral encephalitis and identified a lower frequency of the TLR3 rs3775291 C/T polymorphic genotype TT in infected individuals." (PMID 40831704, 2025). "The proclivity for HSV to selectively cause encephalitis arises from the dependency of the CNS on intact TLR3 signaling for protection against HSV, whereas this pathway is not obligately required for protection against HSV in other organ systems." (PMID 37097753, 2023). "The homozygocity for the wild type allele was present in 53.3% of cases of symptomatic TBEV infection and in 62.5% of cases of encephalitis or myelitis, so higher TLR3 expression was associated with a more severe manifestation." (PMID 28646884, 2017). "Humans with specific defects affecting TLR3 signaling have increased susceptibility to encephalitis, with mutations described in UNC93B, TRAF3, TRIF, and TLR3." (PMID 23606868, 2013). "In humans, HSV infection is also recognized by TLR3, evidenced by the finding that a deletion in TLR3 increases the risk of encephalitis in children and inhibits HSV-mediated stimulation of IFN-β, IFN-γ, and IL-6 in fibroblasts." (PMID 23435233, 2013). "Interestingly, TLR3 has been shown to play an important role in protection against the flavivirus West Nile Virus (WNV), since mice deficient in TLR3 are more vulnerable to severe forms of encephalitis caused by this virus." (PMID 39599884, 2024). "Our patients therefore underwent whole exome sequencing (WES) to test the hypothesis that their encephalitis may be associated with defective TLR3 signaling." (PMID 32936395, 2020). "Patients with impaired TLR3-mediated responses show an elevated susceptibility to Herpes Simplex-1 Virus (HSV-1)-mediated encephalitis by encoding TLR3-deficient alleles, or by encoding deficient TRAF3, TBK1 and TRIF molecules, leading to impaired TLR-3 signaling." (PMID 31574965, 2019). "Whether TLR3 deficiency also primes for encephalitis caused by other viruses, such as VZV or RSV, remains to be determined." (PMID 23435233, 2013). "Finally, reduced viral titers in the periphery but penetration into the CNS and lethal encephalitis were observed after West Nile virus infection of Tlr3-deficient mice." (PMID 22570612, 2012). "Finally, TLR3 plays a role in restricting HSV infection evidenced by a recent study showing that humans that bear mutations in TLR3 are predisposed to HSV-associated encephalitis." (PMID 21994567, 2009). "It highlights genetic defects such as deficiencies in MyD88, IRAK-4, NEMO, and TLR3, which lead to distinct clinical phenotypes, for example, increased susceptibility to bacterial infections or herpes simplex virus type-1 (HSV-1) encephalitis." (PMID 41369391, 2025). "At the virus-sensing level, impaired TLR3 signaling has been reported to play a central role in the development of viral encephalitis, especially in HSE after primary infection." (PMID 38997413, 2024). "Our previous studies have demonstrated that JEV activates microglial cells through TLR-3/RIG-I-NF-κB/AP-1 signaling pathway, which leads to release of inflammatory cytokines, chemokines, ROS, and nitric oxide, and cause severe encephalitis." (PMID 37480121, 2023). "Strong evidence for a protective role of TLR3 in HSV-1-mediated encephalitis has come from studies in patients who have inherited defects in the TLR3 gene or genes encoding proteins that mediate TLR3 signaling." (PMID 34440891, 2021). "An example is West Nile virus (WNV) infection which induces inflammatory response in TLR3-dependent fashion, which triggers the breakdown of blood brain barrier (BBB), resulting in enhanced brain infection causing lethal encephalitis in TLR3+/+ mice." (PMID 33498715, 2021).
encephalitis (continued). "Conditioned media from HSV-1 infected microglia selectively primed the TLR3 pathway of astrocytes, highlighting the crosstalk between glial cells during viral encephalitis." (PMID 34696494, 2021). "The effort has been made to highlight the possible role of TLR3 and viral encephalitis in the pathogenesis of amyloidosis." (PMID 33281554, 2020). "Another related example is the West Nile virus, which is aided by TLR3 to gain entry into the central nervous system and induce lethal encephalitis." (PMID 30075008, 2018). "Furthermore, mutations in certain genes, e.g., TLR3 and TBK1, increase the risk of viral encephalitis." (PMID 39203963, 2024). "It is possible that a failure to induce ZBP1-RIPK3–mediated cell death underlies the encephalitis phenotype, although RIPK3 may also function downstream of TNF receptor 1 or TLR3 to induce neuronal death and restrict viral replication." (PMID 37450010, 2023). "The significance of TLR signaling during viral encephalitis has been highlighted by primary human immunodeficiencies in the TLR3 pathway, as well as by in vivo studies with several genetically modified mouse lines that were deficient in selected TLRs or adaptor molecules." (PMID 34696494, 2021). "However, more functional assays are required to investigate the link between TLR3 gene defects and cases of viral encephalitis." (PMID 34696494, 2021). "The significance of TLR3 sensing initiating anti-VZV responses has been inferred from individuals with defects in genes of the TLR3 pathway suffering from severe varicella resulting in VZV encephalitis." (PMID 32038653, 2020). "In this study, we explored the possibility that genetic defects in innate anti-viral immunity, as analogous to Toll-like receptor 3 (TLR3) mutations seen in HSV-1 encephalitis, may explain PUUV encephalitis." (PMID 32936395, 2020). "To investigate whether corilagin inhibits the TLR3 signaling pathway to relieve the inflammatory response, we examined the expression of TLR3 and its downstream molecules in the brain of mice with encephalitis." (PMID 31080403, 2019). "So in the in vivo experiments, the TLR3 signaling pathway was activated in mice with encephalitis." (PMID 31080403, 2019). "Also, the ablation of both TLR3 and TLR4 molecules induced a highly increased susceptibility to encephalitis caused by JEV infection (p = 0.0122)." (PMID 25188232, 2014). "Taken together, these results demonstrate that TLR3-induced signal pathway is essential for the control of neuroinflammation caused by JEV infection, while TLR4 molecules may be dispensable to provide resistance to fatal encephalitis." (PMID 25188232, 2014). "Incomplete penetrance for HSE is well documented in families with heterozygous TLR3 variations, including in individuals infected with HSV-1, as is expected for sporadic encephalitis." (PMID 32936395, 2020). "The present data also showed the increased expression of Tlr3 along with TNF-α at an early phase of JEV infection and it may be involved in virus entry and resultant encephalitis." (PMID 21371334, 2011).
autoimmune disease (27 papers, 2010 to 2026). A disorder resulting from loss of function or tissue destruction of an organ or multiple organs, arising from humoral or cellular immune responses of the individual to their own tissue constituents. "Targeting this pathway represents a promising therapeutic approach for TLR3-driven autoimmune diseases." (PMID 41924269, 2026). "Beyond oncology, TLR3 plays a significant role in the pathogenesis of autoimmune diseases and allergies, where its activation leads to amplified cytokine production and immune cell recruitment, contributing to the exacerbation of symptoms." (PMID 39988665, 2025). "Increased TLR3 mRNA in local tissues is common in autoimmune diseases such as rheumatoid arthritis (RA) and lupus nephritis, wherein increased cytokine production and immune cell recruitment are observed in the inflamed regions." (PMID 39988665, 2025). "While TLR3’s role in cancer demonstrates its potential for both beneficial and harmful effects, similar complexities arise in autoimmune diseases, where TLR3 activation can lead to exacerbated inflammation." (PMID 39988665, 2025). "Similar to the pathogenesis of autoimmune diseases, the pro-inflammatory downstream modulators in the TLR3 pathway are also noteworthy in allergic inflammation in the respiratory tract and skin." (PMID 39988665, 2025). "Since CXCL10 is regulated by TLR3 and is suggested to mediate TLR3-related inflammatory responses in RA, there is potential for the development of TLR3 antagonists as therapeutic options for autoimmune diseases in the future." (PMID 39988665, 2025). "On the other hand, excessive or dysregulated TLR3 signaling can lead to chronic inflammation and tissue damage, exacerbating conditions such as autoimmune diseases, chronic viral infections, and cancer." (PMID 39988665, 2025). "TLR3 plays a crucial role in modulating both innate and adaptive immunity and has been shown to be a critical regulator in cancer, infectious diseases, autoimmune disorders, and allergy." (PMID 39988665, 2025). "Toll-like receptors (TLRS) are membrane-bound receptors that generate innate immune responses, and aberrant activation of TLR3 is common in inflammatory or autoimmune diseases." (PMID 39188323, 2024). "TLR3 has implicated in autoimmune liver disease in animal models, but the role of TLR3 in human autoimmune diseases needs more studies to clarify." (PMID 38322849, 2024). "Secondly, we also examined these phenotypes in the context of the autoimmune disease model of multiple sclerosis, where pretreatment of murine MSCs with TLR3 and TLR4 agonists generates distinct and opposing immunomodulatory effects on EAE." (PMID 27724984, 2016). "TLR3 is further involved in numerous processes within the liver, ranging from regeneration, viral hepatitis infection as well as autoimmune disease." (PMID 24416163, 2014). "Our recent study suggest that activation of innate immune system mediated by TLR3 signaling pathway is of importance in the pathogenesis of virus-induced autoimmune diseases." (PMID 23207548, 2013). "TLR3, together with other endosomal TLRs (TLR7 and TLR9), have been implicated in the pathogenesis of a variety of autoimmune diseases, including primary biliary cirrhosis." (PMID 20936107, 2010). "TLR3 has also been implicated in the autoimmune liver disease in animal models, but more studies are required to clarify the role of TLR3 in human autoimmune diseases." (PMID 20936107, 2010). "TLR3 activation promotes a pro-inflammatory state systemically and locally, serving as a mediator for both protective and detrimental effects across infectious diseases, cancer, autoimmune diseases, and allergy." (PMID 39988665, 2025). "Endosomal Toll-like receptors (TLRs, including TLR3, TLR7, TLR8 and TLR9) play crucial roles in immune responses by recognizing pathogen-associated molecular patterns; however, their aberrant activation is implicated in inflammatory and autoimmune diseases." (PMID 40887497, 2025).
autoimmune disease (continued). "TLR3, -7, -8, and -9 recognize nucleic acids produced in viruses and bacteria, and all TLRs achieve the recognition of endogenous ligands according to inflammatory and autoimmune diseases." (PMID 33829052, 2021). "To date, polymorphisms of TLR3 have been associated with several chronic inflammatory diseases e.g., rheumatoid arthritis, systemic lupus erythematosus (SLE) and osteoarthritis, the first two of which are autoimmune diseases." (PMID 26442097, 2015). "However, the role of TLR3 in the pathogenesis of human autoimmune diseases is less clear." (PMID 20936107, 2010). "Comparison of rules for each disease revealed that TLR3, TLR5, IL18, IL18R1, and IL1R1 genes occurred in rules for all studied diseases, showing good discriminant power among studied autoimmune diseases as visualized by the Andrews curves." (PMID 31396542, 2019). "Double-stranded RNA was shown to induce apoptosis in cultured islets of C57/B6 mice via TLR3 and IFN regulatory factor 3 pathways and repeated injections of poly I∶C have been shown to induce pancreatitis in autoimmune disease-prone MRL-Mp mice." (PMID 25181416, 2014). "Prior human studies have implicated plasma hsa-let-7a-5p in regulating innate immune genes such as TLR3, RIG-I, and MDA5 in AD patients with allergic conjunctival disease (ACD), and in autoimmune disease (vitiligo) through modulation of autophagy and apoptosis." (PMID 41294837, 2025). "Likewise, intracellular nucleic-acid can also induce the production of IFN-beta via nuclei-acid sensors signaling pathways, including TLR7/TLR8-MyD88 signaling pathway, TLR3-IFN-beta signaling pathway and so on in autoimmune diseases." (PMID 36994418, 2023). "From these results, our data also suggest that the modulation of IL-32 through regulation of TLR3/TRIF and RIG-I pathways might be one of the major targets in inflammatory and/or autoimmune diseases, including ocular surface mucosa diseases." (PMID 25754842, 2015).
glioma (27 papers, 2007 to 2026). A benign or malignant brain and spinal cord tumor that arises from glial cells (astrocytes, oligodendrocytes, ependymal cells). "Previous studies revealed that microglia factors stimulated the apoptosis of glioma cells, and the toll-like receptor 3 agonist poly caused microglia to secrete factors that killed glioma cells." (PMID 33133514, 2020). "Both the sequential TLR9 and TLR3 activation protocol and such engineered DC vaccines present promising novel avenues for the application of DCs in glioma therapy." (PMID 41294838, 2025). "Huang's study demonstrated that dual stimulation of TLR3/TLR9 pathways in myeloid cells of the microglia/macrophage lineage enhances glioma suppression efficacy." (PMID 40838069, 2025). "We investigated the phenotypic and functional outcomes of primed-CMs and glioma cell line co-culture following short-term, low-dose TLR3/4 priming." (PMID 38698968, 2024). "Our findings confirmed that the exposure of TLR3/4-activated-MSCs-CMs with glioma tumour cells possibly changes the immunogenicity of the tumour microenvironment and induces immunogenic programmed cell death." (PMID 38698968, 2024). "The results showed significant changes in apoptosis and likely necroptosis-related markers following TLR3/4-primed-MSCs-CMs exposure in the glioma cell line." (PMID 38698968, 2024). "CRNDE was also found to regulate the occurrence and development of glioma through the TLR3-NF-κB-cytokine signaling pathway." (PMID 33767729, 2021). "For example, DC stimulation with Toll-like receptor 3 (TLR3) agonists enhances the anti-tumor immune response to anti-PD-1 therapy in the orthotopic GL261 glioma model." (PMID 30764570, 2019). "Using an orthotopic mouse glioma model, we investigated the immune response after treatment with TLR3 agonist Poly(I:C) alone and in combination with anti-PD-1." (PMID 29755681, 2018). "•Low-dose treatment of TLR3/4 agonists increases glioma cell death and reduces cell migration." (PMID 38698968, 2024). "The high expression of TLR3 in lower grade glioma (LGG) and LUSC; FASLG in LGG, UVM, KIRC, and THYM; RIPK3 in LGG, KIRC, and LUSC; RIPK1 in LGG and THCA; FAS in LGG, UVM, and THYM; MLKL in LGG, UVM, and LUAD; FADD in LGG and HNSC; and TNF in UVM and CESC was associated with poor survival." (PMID 35748782, 2022). "In addition to human astrocytes, our preliminary data indicate U87 human glioma cells also express functional TLR3 (unpublished observations), suggesting the clinical relevance of direct TLR3 stimulation on glioma cells." (PMID 17295916, 2007). "Using a murine glioma model, we investigated a modified DC vaccine strategy involving the synergistic ex vivo activation of TLR9 and TLR3 with CpG ODN and poly(I:C), respectively." (PMID 41294838, 2025). "While several studies report effects of TLR3, TLR7 and TLR8 signaling in gliomas, their overall roles remain context dependent and incompletely defined while the functions of TLR5 and TLR10 are largely underexplored." (PMID 41157253, 2025). "Further pilot studies have been testing glioma antigen peptides in combination with imiquimod and Poly-ICLC (Hiltonol®), which is a TLR-3 agonist against recurrent ependymomas (NCT01795313) and pediatric glioma (NCT01130077), respectively." (PMID 37605389, 2024). "As shown by the bean plot, 7 genes (RIPK1, RIPK3, FAS, FADD, FASLG, TLR3, and TNF) were upregulated in the glioma tissues with p <0.001." (PMID 35719998, 2022). "Up to date, TLR2, TLR3, TLR4, TLR7, and TLR9 have been intensely studied in glioma, while less or missing information is available regarding the mechanisms of TLR1/TLR6 (dimerizes with TLR2), TLR5, TLR8 (dimerizes with TLR7), and particularly TLR10." (PMID 34715891, 2021). "Activation of TLR3, TLR4, and TLR9 has been reported to reinforce the antitumor response to anti-PD-1/PD-L1 and exhibit immune checkpoint delayed resistance in glioma cells or animal models." (PMID 34715891, 2021).